RNU7-19P (RNA, U7 small nuclear 19 pseudogene)
Synonyms: U7.19
Gene: Small nuclear RNA gene on chromosome 3 (73,027,808 to 73,027,873, forward strand). Ensembl gene ENSG00000238959.
Homologues: Orthologues: macaque U7 (97% identical). Paralogues in human: RNU7-20P (86% identical), RNU7-7P (86% identical), RNU7-73P (85% identical), RNU7-1 (83% identical), RNU7-12P (83% identical), RNU7-10P (82% identical), RNU7-14P (82% identical), RNU7-23P (82% identical), RNU7-35P (82% identical), RNU7-3P (82% identical), RNU7-66P (82% identical), RNU7-125P (80% identical), and 140 more.